CD4 (CD4 molecule)
Diseases named in the same sentence as CD4 in open-access papers (continued):
Sharing a sentence is not in itself a finding about the gene and the disease.
tumor (continued). "For instance, tumor-secreted TGF-β favors the polarization of CD4+ T cells in Treg cells in PC mouse models." (PMID 34439114, 2021). "In 10 of 12 patients, a CD8+ T cell tumor-specific response was found, and in 5 of 12 a CD4+ response was found." (PMID 34210820, 2021). "The evaluation of the CD4+CD25+Foxp3+ T cells determined that the administration of TEXomiR significantly (p < 0.05) decreased the tumor-infiltrated regulatory T cells compared with the PBS-treated group." (PMID 33987190, 2021). "We suggest that IHC examination is better suited to discriminate intratumoral CD4+ T cells from CD4+ T cells that are restricted to the tumor periphery." (PMID 33177208, 2021). "CD4 + T-cells can play an important role in directly killing tumour cells, influencing the active immune response within the tumour microenvironment, and increasing the activity of B-cells and cytotoxic CD8 + T-cells in secondary lymphoid organs." (PMID 33983492, 2021). "In contrast, similar to the notion that the tumor-targeting helper CD4 T cell is usually beneficial in the HCC stage, loss of specific subtypes of CD4 T cells that presumably recognize a neoantigen is important in the progression from NASH to HCC." (PMID 34065108, 2021). "DC2 migration led to CD4+ T cell–dependent tumor control through the repolarization of TAMs toward an inflammatory M1-like phenotype." (PMID 34283809, 2021). "The presence of tumor-infiltrating CD8+ T cells, CD4+ T helper 1 cells, and CD103+ DCs is associated with improved responses to cancer immunotherapy." (PMID 34354077, 2021). "Anti-TNFR2 monotherapy and combinatory therapy significantly reduced the percentage of Foxp3+ Tregs in CD4+ T cells in tumor tissue, with the combination therapy showing a stronger effect." (PMID 34900985, 2021). "Not only does the hypoxic tumor promote regulatory T cell (Treg) homing to the TME, but tumor-derived CD4+CD25+FoxP3+ Tregs have been found to be more suppressive of cytotoxic lymphocytes (CTLs) than normal Tregs." (PMID 33869008, 2021). "The expression of CCNA2 and CKAP2L showed positive association with infiltrating levels of B cells, CD8+ T cells, CD4+ T cells, neutrophils, macrophages, and dendritic cells, but were weakly positive with tumor purity." (PMID 33927744, 2021). "CD4+ T cells were significantly higher in obese mice (p < 0.0001) before tumour engraftment; however, from day seven CD4+ frequencies dropped slightly in obese mice while in lean mice the population increased, with not more significant differences." (PMID 34445503, 2021). "In particular, the change in serum CD4 was correlated with the infiltration of CD4+T cells in the tumor microenvironment." (PMID 34258299, 2021). "Intratumoral administration of OX40L-expressing DCs promoted the generation of tumor-specific CD4+ and NK T cells, contributing to impaired tumor growth." (PMID 34277638, 2021). "CD8+T cells or CD4+T cells were depleted in tumor-bearing Balb/c mice by intraperitoneal (IP) injection of anti-CD8 or anti-CD4 antibodies, respectively." (PMID 34373258, 2021). "Specifically, based on the normalized expression of cell subtype–specific markers, we identified nine macrophage/monocyte subtypes, four CD8+ T cell subtypes and 6 CD4+ T cell subtypes, nine tumor subtypes, and many other stroma and immune cell subtypes." (PMID 33917869, 2021). "Our model incorporates the well-known mechanism of CD4+ T cells helping in the activation of CD8+ cytotoxic T cells in the presence of tumor cells." (PMID 34559809, 2021). "Compared with adjacent normal lung tissues, more CD45+ hematopoietic-derived cells were observed in tumor samples, and CD4+ T cells were the largest cell population in TILs, suggesting that TILs play an important role in tumor progression." (PMID 33747957, 2021).
tumor (continued). "Binding of anti-Gal to inserted α-gal glycolipids initiates uptake of tumor cells and cell membranes by APCs, followed by effective activation of tumor-specific CD4+ and CD8+ T cells and destruction of injected tumors and of distant metastases." (PMID 34805272, 2021). "The immune response is characterized by the infiltration by both CD4 and CD8 T-cells, with CD4 T-cells, following activation by MHC class II on the surface of the tumor cells, secreting cytokines that cause the maturation of the CD8 T-cells." (PMID 33659771, 2021). "Relative concentrations of IL6 and TGFβ in tumor tissues balance the differentiation of coexisting CD4+ RORγt+ Th-17 cells and regulatory CD4+ FoxP3+ RORγt+ IL17-negative T cells." (PMID 34804993, 2021). "Similar to macrophages, dendritic cells (DCs) play an integral role in the adaptive immune system owing to mature DCs cross-present antigen to CD8+ and CD4 + T cells, which stimulate them to eliminate tumor cells." (PMID 34845974, 2021). "Amongst, CD4+CD25+ Tregs cells within tumor microenvironment (TME) called tumor-infiltrating Treg cells (TI-Tregs) have the critical role in cancer immune escape." (PMID 34055618, 2021). "In this context, CD8+ CTL can still mediate anti-tumor activity, although an altered balance between regulatory and effector CD4+ T-cells, with effector cells that prevail." (PMID 34771694, 2021). "In melanoma it was already shown that enhanced CD4+ T-cell responses contributed to increased anti-tumour CD8+ T-cell responses." (PMID 34445385, 2021). "Abundantly detectable in MPM TME they activate tumor-promoting Treg and inhibit tumor-suppressing CD4+ and CD8+ T cells." (PMID 33562138, 2021). "The CTLs must be primed by their interactions with dendritic cells (DCs), CD4+ T-cells, and natural killer cells and further activated to form effector CTLs for killing tumor cells." (PMID 33802331, 2021). "Our results set forth exhausted CD4 T cells at the tumor site as players of response to PD-1 blockade." (PMID 33332284, 2021). "Although CD69 is generally associated as the earliest activation cell surface marker on leukocytes, it has been reported that CD25−FoxP3−CD69+ cells from a tumor-bearing mouse can inhibit CD4+ T-cell proliferation in vitro and in vivo." (PMID 34769406, 2021). "In a translational approach, we sought to evaluate the effects of activin-A on anti-tumor responses by human lung tumor-infiltrating CD4+ T cells from NSCLC patients." (PMID 34548096, 2021). "Further evaluation of the tumor and spleen tissues revealed that there was significant induction of CD4+ and CD8+ T cell populations in the BME-fed group." (PMID 34765739, 2021). "CD4+ T cells can also provide help to B cells via CD40/CD40L and p-MHC II/TCR interactions which drive antibody responses to tumor-associated antigens." (PMID 33708224, 2021). "Multiepitope vaccines designed to elicit tumor-specific CD4+ T cells have potent anti-tumor activity." (PMID 34946546, 2021). "Although CD8+ cytotoxic T lymphocytes (CTLs) play an important role in tumour regression, CD4+ cells are necessary for CTLs to enter tumour tissue." (PMID 33811453, 2021). "Immunization with this IL-15:IL-15Rα cancer vaccine delayed tumor growth in mice by inducing effector memory CD4+ and CD8+ cells and effector NK cells which are tumor-infiltrating." (PMID 34439192, 2021). "Results showed that mRNA expression levels of these genes were significantly increased in tumor-infiltrating CD4+ T cells compared with the cells from the PB of TNBC patients." (PMID 33301062, 2021). "On the other hand, the infiltration of activated memory Tcells CD4 (CD4+T cells), which promote tumor immunity, is down-regulated." (PMID 34307389, 2021). "CD4+ T helper 1 (Th1) cells play a role in protecting against tumor growth, whereas CD4+ Th2 and CD4+ FOXP3+ Treg cells promote tumor growth." (PMID 34680248, 2021).
tumor (continued). "This initial immunity to tumor implantation is dependent on cross-presenting cDC1 and requires CD40 to generate both CD4 and CD8 T cell responses to tumor-associated antigens in the draining lymph node." (PMID 33968757, 2021). "We showed that tumor Ag–specific CD4 T cells accumulate at tumor sites, where they are found at higher proportions than in the circulation, supporting their involvement in direct or indirect antitumor effector functions in situ." (PMID 33332284, 2021). "This was accompanied with a reversal in the zymosan-mediated increase in frequencies of IFN-γ+ Th1 cells, as well as a small but significant increase in the frequency of CD4+Foxp3+ Treg cells primarily in the tumor-draining lymph nodes." (PMID 34127673, 2021). "CD4+ T cells have a central role in antitumor immunity since they regulate the functions of the majority of the tumor-infiltrating leukocytes, including CD8+ T cells, NK cells, macrophages, and DCs." (PMID 34072260, 2021). "For example, tumor-infiltrating Tregs (C08_CD4.CTLA4, C10_CD4.CXCL13) and exhausted T cells (C04_CD8.LAYN) clustered together, demonstrating a huge difference between these cells and others." (PMID 33674641, 2021). "Next, we then performed a correlation analysis between PLAGL2 and tumor-infiltrating immune cells, including B cells, CD4+T cells, CD8+T cells, macrophages, neutrophils, and DCs by the TIMER database in GBM patients to evaluate the immunotherapy effect." (PMID 35222518, 2021). "The amount of these cells is higher in the glioblastoma tumor microenvironment and suppress cytotoxic NK cell, CD4+- and CD8+ T cell function." (PMID 34485282, 2021). "In CTCL, cytotoxic CD4+ T cells act through a granzyme-perforin-dependent pathway to achieve tumor cell killing, similar to cytotoxic CD8+ T cells." (PMID 34795254, 2021). "Based on our observations we believe that perhaps epigenetic interaction between GBM and tumor infiltrating CD4+ T cells is responsible for the immunosuppressed state seen in the GBM patients." (PMID 34012510, 2021). "In the tumor tissues of patients with high IL-34 expression, the proportion of these immune cells was higher except for that of activated CD4+ memory T cells." (PMID 34336646, 2021). "Our results show that ACKR4 knockdown tumors have fewer CD4+ T-cells but a higher proportion of exhausted CD4+ T-cells in their tumor microenvironment than the control group." (PMID 34638505, 2021). "Our in vivo experiment further suggested that the targeted silence of CRNDE-h in CD4+ T cells reduced the Th17 cell proportion in the tumor-infiltrating T cells and inhibited the tumor growth in the tumor-transplanted mice." (PMID 33495437, 2021). "As a functional outcome of enhanced DC2 migration, CD4+ T cell activation was significantly augmented in the dLN and tumor of Batf3–/– mice." (PMID 34283809, 2021). "CD4 T cells provide B-cell help for the production of class-switched tumor-reactive antibodies, mainly of the IgG2a (mice) or IgG1 isotype (humans)." (PMID 34201655, 2021). "In our study, the relationship between hub genes and tumor-infiltrating immune cells (B cells, CD4+ T cells, CD8+ T cells, neutrophils, macrophages, myeloid DCs and MDSCs) was tested via the TIMER 2.0 database." (PMID 34955857, 2021). "Bilateral tumors and draining lymph nodes (dLNs) were collected 13 days after tumor inoculation to analyze the TCR repertoire of CD4+ and CD8+ T cells." (PMID 34759926, 2021). "On the other hand, PDT-induced tumor cell death releases DAMPs that include multiple tumor-specific antigens, which are then presented by the DCs and other APCs to the CD4+ and CD8+ T cells 120,121, thereby eliciting an anti-tumor immune response." (PMID 34158855, 2021). "Enhanced CD27 expression on immune cells such as CD8+ and CD4+ T cells residing in the tumor microenvironment, FoxP3-expressing CD4+ T, and CD3−NK1.1+ natural killer (NK) cells augments the activities of these cells." (PMID 32902664, 2021).
tumor (continued). "Although tumor-infiltrating CD8 T cells, often referred to as TILs, are the most-studied T-cell type in cancer, CD4 and DN T cells are both commonly found in the tumor microenvironment." (PMID 33653826, 2021). "CD4+ T cells were predominantly scored ≤ 1 in perivascular spaces in both primary (76.9%) and recurrent (92.3%) tumours." (PMID 34676050, 2021). "It is becoming increasingly evident that in the context of anti-tumor immune response CD4+ T-cells are essential for the generation and maintenance of effective anti-tumor CD8+ cytotoxic T-cell response." (PMID 34012510, 2021). "The tumor antigen-specific CD4 + T cells in cancer immunity are a key strategy for tumor prognosis and treatment." (PMID 34490269, 2021). "Tumor-specific CD8+ and CD4+ T cells infiltrate the tumor site after the recognition of tumor-specific or tumor-associated antigens through HLA class I and class II molecules, respectively, which facilitate the immune mechanisms in synergy with B cells." (PMID 34867958, 2021). "This group suggested that API treatment (150 mg/kg) significantly suppressed the growth of B16-F10 xenograft tumors and regulated the sensitivity of tumor to immune killing by increased the abundance of CD4+ and CD8+ T cells." (PMID 34239802, 2021). "Prophylactic administration of SA–4-1BBL to tumor-challenged mice was shown to prevent tumor growth, and this was dependent on CD4+ T cell, NK, and IFN-γ production." (PMID 34277638, 2021). "A successful cancer immunotherapy will require careful balancing of the CD4+ TH compartment in order to orchestrate essential efforts that mediate tumor regression." (PMID 34012451, 2021). "Collectively, these results suggest that the use of anti-CD4 treatment increases effector function, tumor reactivity, and intratumoral infiltration of endogenous CD8+ T cells in this ACT combination model." (PMID 34493727, 2021). "In contrast, tumor-infiltrating IFN-γ-producing CD4 + and CD8 + T cells were reduced in Ccng2−/− mice." (PMID 34452627, 2021). "Among CD4+ T cells, central memory cells are primarily responsible for immune memory and immune protection during tumor metastasis while effector memory cells play essential roles in regulating the expression of adhesion molecules and chemokine receptors." (PMID 33968780, 2021). "For the prediction of the immune signature of TH17 cells, inflamed (tumor, CD4) was kept in the model." (PMID 33791196, 2021). "The miR-16 is known to induce apoptosis of tumor cells, induce polarization of macrophages into the M1 phenotype, and activate CD4+ T cells by downregulation of PD-L137,38." (PMID 33859336, 2021). "When vaccinated with P2Et-pretreated 4T1 cells, the primary tumor growth was improved by yielding IL-2, TNFα, IL-4, IL-5, and IFNγ-producing CD4+ and CD8+ T lymphocytes." (PMID 34948368, 2021). "Intriguingly, once the intrinsic TGFB signaling pathway is blocked, CD4+ T cells were observed to promote the healing of tissues around the tumor." (PMID 34145032, 2021). "To investigate the impact of the CD80 deactivation in tumor cells on anti-tumor immune reactions, we depleted CD4+, CD8+, natural killer (NK) 1.1+ cells, or macrophages in mice bearing TC-1- and TC-1/dCD80-1-induced tumors." (PMID 33923750, 2021). "In this study, we describe that mono-palmitoylation directly on the N-terminus of synthetic long peptide enhances CD8+ and CD4+ T cell activation and induces in vivo tumor suppression." (PMID 34141869, 2021). "This because CTLs only carry out their potent anti-tumor function after priming and activation by DCs, CD4+ T cells, and NK cells (which specifically respond to MHC class I downregulation, which “hides” tumors from other immune cells)." (PMID 33668730, 2021). "Studies have found that the expression of tumor-related genes is related to the infiltration level of CD4+ T cells, CD8+ T cells, macrophages, etc.." (PMID 35047403, 2021).
tumor (continued). "Then, CD4+ T cells stimulated tumor-specific immunity and inhibited tumor growth after recognizing neoantigens in mice." (PMID 34513673, 2021). "In accordance with the notion, a recent study has demonstrated that CD4+ T cells play a critical role in the anti-tumor effect of CART cell therapy." (PMID 33462228, 2021). "The efficacy of DCs primed with 750 ng/ml of rhSPAG9 (SPDCs) was compared with DCs primed with autologous tumor lysates (TLDCs), to induce CD4+, CD8+ T cells and activating NK cells." (PMID 34493268, 2021). "Altogether, the study suggested that inhibition of BTK in dendritic cells enhanced maturation and activation of dendritic cells and accelerated CD4+ T cell growth, which contributes to reshaping the tumor microenvironment during cancer development." (PMID 34063667, 2021). "The percentages of M1 macrophages and CD4+ T cells in spleen and tumor tissues were found to increase following YPF administration." (PMID 34639167, 2021). "A putative TAA released by proliferating or dying tumor cells would be presented by macrophages or dendritic cells to stimulate CD4+ and then CD8+ T lymphocytes and B cells, provided proper co-stimulatory signals are available." (PMID 34717628, 2021). "In particular, CCL19 is a chemotactic factor involved in recruiting CD4+CD25+CD69- T-regs to zones of T cell infiltration in the tumor micro-environment." (PMID 34298673, 2021). "By contrast, CD4+ regulatory T cells suppressed anti-tumor immunity, thereby limiting the long-term efficacy of cancer immunotherapy." (PMID 33795528, 2021). "Sure enough, subpopulations of CD4+ T cells were discovered to hinder effective immune responses against cancer cells as well as to interact with tumor vasculature to promote tumor angiogenesis." (PMID 33514440, 2021). "In our study, tumor-infiltrating T lymphocytes, especially CD4+ T lymphocytes, were significantly increased in IRF3KO mice compared to WT mice." (PMID 34768716, 2021). "In a word, here we propose a model involving interplay between neutrophils, CD4+ T cells, and tumor cells in the GC tumor environments." (PMID 34185422, 2021). "Even though CTLs are required for anti-tumor immunity, CD4+ T cells are also at the forefront of improving immunotherapies through their ability to provide help and amplify the CTLs response, making these cells an important target for cancer immunotherapy." (PMID 33708224, 2021). "We showed that the MMC-treated IL-15:IL-15Rα-B16F10-OVA vaccine inhibited the tumor growth of B16F10-OVA by enhancing splenic central memory CD8+ T cells, tumor-infiltrating NK cells, and tumor-infiltrating effector memory CD4+ and CD8+ T cells." (PMID 34439192, 2021). "Overall, these recent clinical advances corroborate the robust findings from preclinical models that CD4+ T cells play a fundamental role in driving and sustaining meaningful anti-tumour immune responses." (PMID 32457487, 2021). "A hyperactive immune response in local tumor tissues blocks attacks from beneficial immune cells, such as NK cells and CD4+ T cells." (PMID 35127714, 2021). "Further, our data suggested the CD4+T cells have undergone approximately five cell divisions, indicating that the ex vivo injected CD4+T cells were able to exert a viable robust anti-tumor response." (PMID 33918403, 2021). "CIBERSORT analysis indicated that NTF3 expression was positively correlated with CD4+ cells, mast cells, NK cells, macrophages and B cells in the tumor microenvironment." (PMID 34938753, 2021). "An increased tumor-infiltrating CD4+ T-cell count and an increased CD4+:CD8+ T-cell ratio have been demonstrated to be significantly associated with improved patient response to BCG156 in athymic nude mice." (PMID 33495451, 2021). "Highest mean IRS values were observed for tumor-associated macrophages marker CD204 (meanCD204: 7.16) and T cell marker CD4 (meanCD4: 5.74)." (PMID 34063518, 2021).